MYC (MYC proto-oncogene, bHLH transcription factor)
Diseases named in the same sentence as MYC in open-access papers (continued):
Sharing a sentence is not in itself a finding about the gene and the disease.
breast cancer (continued). "Results showed that TrkA WT-overexpressing cells had significantly higher mRNA levels of SOX2 and MYC, which are two known STAT3 target genes frequently associated with breast cancer cell stemness and aggressiveness." (PMID 34066153, 2021). "miR-302b maintain SOX2 and c-MYC to produce cytokine-induced cancer stem cell-like properties in breast cancer cell co-cultured with immature adipocyte; whilst miR-302b in breast cancer targets RUNX2, an activator of PI3K/AKT signaling." (PMID 33482868, 2021). "In summary, these results suggested that the inhibitory effect of CLDN6 on breast cancer growth was c–MYC–dependent." (PMID 35008557, 2021). "The GSEA result also revealed that the high expression of NEK2 groups in the TCGA breast cancer database were significantly correlated with G2M checkpoint, E2F, MYC targets signaling pathways." (PMID 34834441, 2021). "Splicesome inhibition has been proposed as an effective therapeutic approach for treating MYC-driven breast cancers." (PMID 33879154, 2021). "The expression of miRNAs miR-17-5p and miR-20a-5p that suppress the MYC gene is activated in breast cancer cells by the c-Myc factor, which demonstrates their participation in the negative regulation of the expression of this factor." (PMID 34440124, 2021). "The amplification of Her2, S100A and CCND1 have biological significance in breast cancer pathology, and amplification of c-MYC is related to high-grade malignancy." (PMID 34868925, 2021). "An MYC-driven breast cancer tumor model was used to demonstrate decreased pyruvate-to-lactate conversion with reduced MYC-driven tumor progression and increased pyruvate-to-lactate conversion with cancer recurrence." (PMID 33925445, 2021). "Using technology originally adapted for HER2/neu assessment in breast cancer, we developed a new clinical grade, automated chromogenic assay to assess MYC and PTEN status simultaneously on a single biopsy slide." (PMID 34062284, 2021). "For ovarian (OC) and head and neck squamous cell carcinoma (HNSCC), this was half of all cases with MYC amplifications, while in breast cancer (BC) this was ∼90% cases." (PMID 33868369, 2021). "For example, MYC amplifications are reported in as many as 48% of breast cancers and as many as 78% of osteosarcomas." (PMID 34503295, 2021). "Breast cancer EV-derived miR-105 has been shown to induce the oncogenic protein MYC and activate the MYC pathway in CAFs at the future PMN." (PMID 34943937, 2021). "Previous studies have demonstrated that triple-negative breast cancer had a higher proportion of MYC gene amplification and increased mRNA expression than other breast cancer molecular subtypes." (PMID 33968723, 2021). "In MCF7 cells, L1 transposons were found to be bound by a total of 99 TFs, including ESR1, MYC, FOXA1 and E2F1, which have well-established and critical roles in cell growth and division and have been linked to breast cancer development." (PMID 34070697, 2021). "A correlation between MYC expression and metastasis was also shown in non-small cell lung cancer, breast cancer, and gallbladder cancer." (PMID 34440124, 2021). "A previous study in breast cancer found frequent MYC co-amplifications with multiple genes in the 8q chromosomal region." (PMID 33868369, 2021). "In oncogene mutated cancers like KRASG12D-driven PDAC (Pancreatic Ductal Adenocarcinoma) and MYC/KRAS or MYC/ERBB2-ablated breast cancer, cancer cells predominantly rely on OXPHOS for energy production." (PMID 34557865, 2021). "For example, in addition to let-7, two other miRNAs that control the expression of the MYC gene are involved in coordinating the response to estrogen in breast cancer cells: miR-21-5p and miR-98-5p." (PMID 34440124, 2021).
breast cancer (continued). "For example, in general, basal-like breast carcinoma has been known to harbor mutations involving BRCA1, CCNE1, AKT3, or MYC; however, these genes were largely wild type, and NOTCH1 mutations were relatively common in our SeC-EOs." (PMID 34638295, 2021). "Positive controls showed expected staining for OCT4 and NANOG in seminoma, SOX2 in skin, KLF4 in breast carcinoma, and c-MYC in normal colon." (PMID 33816543, 2021). "c-MYC is also a direct target and a coregulator of ERα, it can act synergistically with ERα to induce breast cancer cell proliferation." (PMID 33489906, 2020). "We found that human breast cancer patient tumors have increased numbers of integrin αvβ3-positive macrophages, and we provide new evidence that human breast cancer TAMs express MYC." (PMID 32685002, 2020). "We observed that G2M checkpoint, MYC target V2, and breast cancer ZNF217 were differentially enriched in the high NUSAP1 expression phenotype." (PMID 32226503, 2020). "This association was evident in two out of four datasets for MYC-PML and four out of four for PIM1-PML, when accounting all breast cancer subtypes." (PMID 31570853, 2020). "Specifically, MYC amplification mediates the glutamine-related metabolic rewiring in breast cancers, that promotes the excessive uptake of glutamine by inducing the expression of glutamine transporters and glutamine-metabolizing enzymes." (PMID 33489906, 2020). "Our study, however, suggests that in breast cancer some specific effects must be ascribed directly to the increased dyskerin expression, even independently from MYC." (PMID 33255756, 2020). "We found a significant correlation (rho = 0.41; p = 0.02) between CDK7 and MYC expression in patients with ESR+ breast cancer treated with tamoxifen." (PMID 32340192, 2020). "During breast cancer metastasis, the regulatory effect of c-MYC on a broad segment of lncRNAs opens up a new area of c-MYC activity." (PMID 32929060, 2020). "Collectively, our data strongly suggested that PRKD3 likely promote the cell proliferation in the breast cancer cells by activating ERK1‐c‐MYC axis." (PMID 31944568, 2020). "MYC restrains breast cancer cell motility and invasion through transcriptional silencing of integrin subunits." (PMID 32098783, 2020). "In order to confirm that PRKD3 activated ERK1/c‐MYC axis in the breast cancer cells, we analysed the amounts of the phosphorylated and total ERK1/2 or c‐MYC by performing Western blotting." (PMID 31944568, 2020). "MYC amplification occurs in ~25% of all breast cancers and occurs more frequently in triple negative breast cancer (TNBC) (up to 50%).4,5 MYC gene amplification is associated with risk of relapse, poor prognosis, and death." (PMID 31942031, 2020). "Next, we tested a c-MYC/Max dimerization inhibitor that has shown anti-cancer activity in breast cancer xenografts." (PMID 32759815, 2020). "MYC is amplified in breast cancer and has been reported to be overexpressed in 30–50% of high grade breast cancers." (PMID 33176745, 2020). "mTORC1/MYC hyperactivation increases HSP activation in breast cancer cells by upregulating O-GlcNAc transferase (OGT)." (PMID 33081387, 2020). "FOXP2 negatively regulates stem cell-associated factors—such as c-MYC, OCT-4, and CD44—in breast cancer, resulting in a putative tumor/metastasis suppressor." (PMID 31936744, 2020). "MYC is an estrogen-regulated oncogene that is overexpressed in many cancer types including breast cancer." (PMID 32340192, 2020). "MYC amplification is found in 21% of patients across 33 different cancers, particularly breast cancer, lung squamous cell carcinoma, uterine carcinoma, esophageal carcinoma, and ovarian cancer." (PMID 33322239, 2020). "The challenge is now to identify the breast cancer metastasis relevant lncRNA targets of c-MYC, and determine their functions." (PMID 32929060, 2020).
breast cancer (continued). "We found that intratumoral adipocyte-low tumors significantly enriched for cell cycle and cell proliferation gene sets such as E2F targets, G2M checkpoint, MYC targets V1, and MYC targets V2 in the whole breast cancer cohort of TCGA." (PMID 32796516, 2020). "There is evidence that MYC amplifies transcription of RNA pol III genes when RNA pol III genes are hypomethylated in breast cancer, specifically the nc886 gene, a short noncoding RNA, which has been shown to be occupied by BRF1 and deregulated in cancer." (PMID 33176745, 2020). "We next sought to determine if the fatty acid metabolism gene signature of the MYC HME cells is representative of specific molecular subtype of breast cancer." (PMID 31942031, 2020). "Within the genomics of tumors, implication of the rearrangement of the RET proto-oncogene in thyroid cancer and amplification of MYC in cutaneous angiosarcoma after irradiation of the chest wall for breast cancer are known." (PMID 33019945, 2020). "In ER+ breast cancer cells, E2-ERα can indirectly reduce miR-26a expression by upregulating c-MYC, which has been reported to inhibit the expression of several miRNAs." (PMID 32265934, 2020). "The integration of the survival data analysis, gene set enrichment analysis, and the analysis of the breast cancer histopathological images revealed that MKK3 can promote TNBC tumorigenesis through the activation of the MYC transcriptional program." (PMID 32873298, 2020). "We show for the first time that TAMs from human patient breast cancers express integrin αvβ3 and they also express MYC." (PMID 32685002, 2020). "We have determined that besides its well-defined function in the p38-inflammatory pathway, MKK3 can induce MYC-dependent epithelial-to-mesenchymal transition in breast cancer patients in part through upregulation of EIF5A, EIF5AL1, and SNAI1 genes." (PMID 32873298, 2020). "This trend was also consistent across a number of cancers: in particular, highly rewired TFs such as BHLHE40, JUND, and MYC behaved similarly in lung, liver, and breast cancers." (PMID 32728046, 2020). "To date, only one study has identified MZT2B as a target for MYC in gene expression data for breast cancer cell lines and tissues." (PMID 33351778, 2020). "In short, we suggested that PRKD3 functions as an upstream regulator of ERK1/c‐MYC axis and promotes the proliferation of the breast cancer cells." (PMID 31944568, 2020). "TCGA analyses showed that MYC, PIK3CA, and CDKN2A/B are the most frequently amplified, mutated, and deleted genes, respectively, in breast cancer." (PMID 32498332, 2020). "In line with this notion, we found that PML is associated to the promoter regions of MYC and PIM1, consistent with their direct correlation in breast cancer specimens." (PMID 31570853, 2020). "In summary, our mechanistic studies provide evidence that CDK7 activates ER-α phosphorylation at Ser118 which enhances the transcription of MYC in ER+ breast cancer (pathway 1)." (PMID 32340192, 2020). "USP22 promotes deubiquitination of c-MYC in breast cancer cells, resulting in increased levels of c-MYC." (PMID 32268558, 2020). "Our results demonstrate that CESC patients with high NUSAP1 expression were enriched in the G2M checkpoint, MYC targets, and breast cancer ZNF217, which are closely related to the early onset of cancer and the risk of tumor progression and metastasis." (PMID 32226503, 2020). "Beta-sitosterol bound to EGFR/MYC, inhibiting breast cancer growth through ErbB or Estrogen pathway." (PMID 32978480, 2020). "Our study provided the evidence to support that the PRKD3/ERK1/c‐MYC pathway play an important role in breast cancer progression." (PMID 31944568, 2020).
breast cancer (continued). "Over the past decades, MYC became a well-established and highly-appealing therapeutic target in breast cancer." (PMID 32873298, 2020). "ELF5 is a transcription factor regulating key genes e.g., FOXA1, EGFR, and MYC, and has been described as potential regulator of anti-estrogen resistance in luminal breast cancer and imatinib resistance in chronic myeloid leukemia." (PMID 32429253, 2020). "Elevated levels of RSPO1 (an activator of the canonical Wnt signaling pathway with essential roles in ovary determination) combined with PVT1 and MYC transcripts were found in human breast cancer tumors than tumors with low levels of MYC." (PMID 32117705, 2020). "Such a pro-proliferative function involves an enhanced breast cancer stemness and transcriptional upregulation of two factors that have a well-established role in breast cancer, MYC and TBX3." (PMID 33217982, 2020). "High MYC targets scores were also associated with clinically aggressive subtypes, triple-negative breast cancer (TNBC) and HER2-positive breast cancer, compared with ER-positive/HER2-negative tumors (MYC v1 and v2, both p < 0.001)." (PMID 33143224, 2020). "Tumors that recurred after PIK3CA inactivation acquired focal amplification of MET or MYC in an in vivo mouse breast cancer model expressing PIK3CAH1047R34." (PMID 32409685, 2020). "c-MYC is known to be over expressed in breast cancer, and its involvement in glutamine uptake and degradation is well reported, as it stimulates surface transporters and glutamine synthetase suppression." (PMID 33318536, 2020). "The cytogenetic locations of BRF2 (8p11.23) and MYC (8q24.21) are on a portion of chromosome 8 known to be amplified in breast cancer." (PMID 33176745, 2020). "Many data in cellular and animal breast cancer models suggest that progesterone exert a cancer promoter role by acting on MYC and CCDN1 genes." (PMID 33266334, 2020). "To develop a metastatic mouse model of MYC-driven breast cancer, we used transgenic WAP-Myc mice, which develop breast adenocarcinomas following two pregnancies." (PMID 33127915, 2020). "Hypermethylation of the PLA2R1 promoter in breast cancer is triggered by cellular myelocytomatosis (c-MYC)-mediated promoter methylation." (PMID 32751713, 2020). "It has been suggested that in ER+ breast cancer cells, E2-ERα can indirectly reduce miR-26a expression by upregulating c-MYC, which has been reported to suppress the expression of many miRNAs." (PMID 32265934, 2020). "Two breast cancers in this series harboured a gain of the 8q24 region, comprising both MYC and the adjacent lncRNA PVT1, which stabilizes the MYC protein and enhances its activity." (PMID 32058674, 2020). "An active Phase I clinical trial, NCT01676753, is assessing MYC overexpression with dinaciclib + pembrolizumab efficacy in advanced breast cancer." (PMID 33322239, 2020). "The results indicated significant enrichment for the previously identified MYC signaling pathway and pathways related to breast cancer development." (PMID 32398735, 2020). "In this study, we aimed to generate a clinically-relevant, MYC-driven metastatic breast cancer mouse model by syngrafting WAP-Myc tumor cells to syngeneic recipient mice." (PMID 33127915, 2020). "Conversely, MYC and Cyclin E1, critical activators of the cell cycle, are more frequently amplified in Black/African American breast cancer patients (30.9% and 9.2%, respectively) than in White patients (20.4% and 3.6%)." (PMID 32873298, 2020).
breast cancer (continued). "Functionally, it exhibits oncogenic effects in colon and breast cancer, and through MYC and it influences taxane sensitivity." (PMID 32887459, 2020). "In particular, in breast cancer MYC induces the expression of the ADHFE1 oncogene, which upregulates glycolysis, Krebs cycle, and amino acids synthesis." (PMID 32932943, 2020). "The shift from glycolysis to OxPhos has also been showed upon MYC/KRAS or MYC/ERBB2 removal in breast cancer cells, and also in glioma cells because of the acquired resistance to phosphoinositide-3-kinase (PI3K)." (PMID 32211323, 2020). "The MYC gene is highly expressed in the basal −like subtype of breast cancer, which is being targeted for treatment in these patients." (PMID 33324444, 2020). "In HER2 positive breast cancer cells AS1842856 restores Lapatinib sensitivity by reducing the FOXO1-mediated MYC upregulation and in ovarian cancer cells AS1842856 prevents the FOXO1-induced senescence by inhibiting the progestin-induced p21 expression." (PMID 31591479, 2020). "GSEA demonstrated that CESC patients with high expression of NUSAP1 were enriched in the G2M checkpoint, MYC targets, and breast cancer ZNF217." (PMID 32226503, 2020). "TNBC tumors express high levels of the MYC oncogene product compared to other breast cancer subtypes." (PMID 32645016, 2020). "Positive controls demonstrated the expected staining pattern for OCT4 and NANOG in seminoma, SOX2 in normal skin, KLF4 in breast carcinoma, and c-MYC in normal colon." (PMID 32019273, 2020). "Human tissues used for positive controls demonstrated positive staining of OCT4 and NANOG on sections of seminoma, SOX2 on skin, KLF4 on breast carcinoma, and c-MYC on colon." (PMID 32850316, 2020). "Human tissues for positive controls showed the expected staining patterns: for OCT4 and NANOG on seminoma, SOX2 on skin, KLF4 on breast carcinoma, and c-MYC on colon." (PMID 32850316, 2020). "Consistent with this a recent study showed a progressive increase in Pol-III activity in a model of breast cancer initiation and progression, which correlated with c-MYC activity." (PMID 30858608, 2019). "To understand the mechanisms and vulnerabilities of MYC-driven breast cancer, we have generated an in vivo model that mimics human disease in response to MYC deregulation." (PMID 31350286, 2019). "The authors suggest that evaluation of c-MYC CNVs after neoadjuvant chemotherapy can be used as a prognostic factor in patients with breast cancer." (PMID 31554154, 2019). "BRD4 has most often been associated with MYC expression, with this regulation seen in multiple myeloma, AML and ER+ breast cancer." (PMID 31652979, 2019). "During the review process of this manuscript, a study demonstrated that c-MYC is critical for the IRE1α-XBP1s pathway in breast cancer cells by directly activating IRE1α expression and potentiating XBP1s transcriptional activity." (PMID 30679434, 2019). "On the other hand, MYC appears to be involved in the functions of both ERα and ERβ, although MYC is upregulated by ERα in breast cancer cells and downregulated by ERβ in prostate cancer cells." (PMID 30979864, 2019). "The SLUG promoter was then activated by MYC, which promoted development of breast cancer stem-like traits." (PMID 30688660, 2019). "It has been reported that MYC can activate WNT in breast cancer, and in our work, Wnt1 was significantly dependent on MYC (with p-value of 0.002)." (PMID 31213036, 2019). "CNVs of c-MYC before and after neoadjuvant chemotherapy with doxorubicin, cyclophophamid and docetaxel in different regimens in breast cancer patients were studied by FISH." (PMID 31554154, 2019). "Tumours with low ATM or high ATR levels in conjunction with MYC overexpression also have worse overall breast cancer-specific survival (BCSS) (p value < 0.05)." (PMID 30746633, 2019).